SIRT3 (sirtuin 3)
Diseases named in the same sentence as SIRT3 in open-access papers (continued):
Sharing a sentence is not in itself a finding about the gene and the disease.
lung carcinoma (continued). "Materials and Methods: Resected samples from 80 pairs of lung cancer was used to prepare tissue array and Sirt3 was stained with immunochemical method." (PMID 34405009, 2021). "Firstly, we performed a tissues microarray by using patients samples and found that the expression level of Sirt3 in lung cancer tissues was considerably higher than that in para-cancerous tissues." (PMID 34405009, 2021). "Sirt3 was also found to be involved in cell proliferation, apoptosis and metastasis in lung cancer cells." (PMID 34405009, 2021). "The results showed that the expression level of Sirt3 in lung cancer cells was much higher than in normal bronchial epithelial cells." (PMID 34405009, 2021). "Taken together, SIRT3 elevation inhibits cisplatin resistance of lung cancer cells through FOXO3/CDT1 axis in vivo." (PMID 33655712, 2021). "RT‐qPCR and Immunoblotting results displayed that mRNA and protein expression of SIRT3 was strikingly inhibited in lung cancer tissues compared with adjacent normal tissue." (PMID 33655712, 2021). "As a radiation responsive gene, Sirt3 also participate in the radiation resistance of lung cancer cells." (PMID 34405009, 2021). "In our present study, we generated an in situ lung cancer model, and we injected the Sirt3 modified cells directly into the lung tissues." (PMID 34405009, 2021). "In order to explore the in vivo effect of Sirt3 on lung cancer, we constructed a mouse lung cancer radiotherapy model, and implanted Sirt3 NC, Sirt3 knockdown, and overexpression Lewis lung cancer (LLC) cells in the left lower lung lobe of C57BL/6 mice." (PMID 34405009, 2021). "Our earlier study supports an essential role of SIRT-3 for TL-induced impairment of mitochondrial function and associated apoptosis in A549 and NCI-H460 lung cancer cells." (PMID 32733649, 2020). "Our previously published findings established an essential role of SIRT-3 for TL-induced impairment of mitochondrial function and associated apoptosis in A549 and NCI-H460 lung cancer cells." (PMID 32733649, 2020). "SIRT3 plays a conflicting role not only in different types of cancer, such as gastric cancer, lung cancer, and colon cancer, but also in malignancies originating from the same types of tissue." (PMID 31817470, 2019). "In KRAS mutant lung cancer cells, it was discovered that Sirt3 was significantly up-regulated in honokiol-treated KRAS mutant lung cancer cells, leading to the destabilisation of its target gene Hif-1α and induction of G1 arrest and apoptosis." (PMID 31877856, 2019). "Additionally, under hypoxic conditions, SIRT3 influences lung cancer progression through the ROS/formyl peptide receptor-1 (FPR1)/HIF-1α axis." (PMID 40710178, 2025). "SIRT3 has been reported to exert its effects on lung cancer through various mechanisms." (PMID 40710178, 2025). "In cancer, SIRT3 was first postulated as a sensitizing agent in lung cancer." (PMID 41425553, 2025). "Moreover, the inhibiting effect of Arg-II on Sirt3 in both melanoma and lung cancer cells is supported by several lines of evidence." (PMID 40177131, 2025). "Subsequently, using the K‐M plotter, we investigated the relationship between the expression of SIRTs and prognostic survival rate in lung cancer patients and found that the high expression of SIRT1, SIRT3 and SIRT4 was associated with better prognosis, respectively." (PMID 39501597, 2024). "Moreover, Melatonin can reverse the Warburg effect in cancer cells by promoting a shift from aerobic glycolysis to oxidative phosphorylation, which can decrease lung cancer development by elevating SIRT3 levels." (PMID 38773972, 2024). "The aim was to investigate whether SIRT3 affected lung cancer development under hypoxic conditions via regulating the ROS-FPR1/ HIF-1α axis." (PMID 37747648, 2023). "We explored whether SIRT3 affects the development of lung cancer by regulating the reactive oxygen species (ROS)-FPR1/HIF-1α axis under hypoxic conditions." (PMID 37747648, 2023).
lung carcinoma (continued). "It has been demonstrated that SIRT3 plays a dual role in lung cancer." (PMID 36117172, 2022). "Furthermore, our findings revealed that SIRT3 elevation inhibited cell cisplatin resistance of lung cancer cells." (PMID 33655712, 2021). "Finally, our in vivo model showed that targeting Sirt3 significantly sensitized lung cancer to radiotherapy." (PMID 34405009, 2021). "We explored whether irradiation has an impact on Sirt3 expression in human bronchial epithelial cell and lung cancer cells." (PMID 34405009, 2021). "Finally, using our in situ lung cancer model, we found that Sirt3 confers the radioresistance of lung cancer in vivo." (PMID 34405009, 2021). "Hence, researchers aimed to determine role of sirtuin 3 (SIRT3) considering its action in cisplatin resistance of lung cancer." (PMID 33655712, 2021). "In contrast, Sirt3 overexpression promoted radioresistance in lung cancer cells." (PMID 34405009, 2021). "The role of SIRT3/FOXO3a/CDT1 axis in cisplatin resistance of lung cancer." (PMID 33655712, 2021). "Consistent with previous reports, we demonstrated that Sirt3 was significantly downregulated in KRAS mutant lung cancer cells compared with normal lung cells, which could be enhanced by honokiol treatment." (PMID 28443025, 2017). "Additionally, the decreased expression of sirtuin 3 (SIRT3) in lung cancer tissues and serum samples could be a promising biomarker for diagnosis with a sensitivity of 86.4%, a specificity of 94%, and a cutoff value of 3.12." (PMID 36614301, 2023). "However, the role of Sirt3 in radiotherapy of lung cancer is unclear." (PMID 34405009, 2021). "Therefore, our results suggested honokiol induced autophagy in KRAS mutant lung cancer cells could be attributed to Sirt3- Hif-1α pathway." (PMID 28443025, 2017). "The activation function of Sirt3 on PI3K-AKT and mTOR pathways has been reported in lung cancer cells, which is similar in HT22 cells showed in our results." (PMID 37891608, 2023). "Mechanically, overexpressed SIRT3 elevates expression of FOXO3a/CDT1 axis, thus, contributing to enhanced cell apoptosis and sensitivity of lung cancer cells to cisplatin." (PMID 33655712, 2021). "Next, we examined the basal expression level of Sirt3 in human bronchial epithelial cells (BEAS-2B), various human lung cancer cells (A549, H460, H1299) by Western Blotting assay." (PMID 34405009, 2021). "The expression patterns of SIRT3, FOXO3, and CDT1 were determined using RT‐qPCR and Immunoblotting in lung cancer." (PMID 33655712, 2021). "Collectively, overexpressed SIRT3 elevates expression of FOXO3a/CDT1 axis, thus, contributing to enhanced sensitivity of lung cancer cells." (PMID 33655712, 2021). "Taken together, SIRT3 regulates FOXO3/CDT1 axis, thus enhancing cisplatin resistance of lung cancer cells." (PMID 33655712, 2021). "In the present study, we checked the expression of Sirt3 in NSCLC cells and tissues from lung cancer patients." (PMID 34405009, 2021). "The elevation of SIRT3, FOXO3, or CDT1 inhibited cell cisplatin resistance of lung cancer cells as well as inhibited viability, proliferation, and invasion in vitro." (PMID 33655712, 2021). "Taken together, results from these inhibitor studies suggest SIRT-1 and SIRT-3 play important roles in mediating TL-induced down-regulation of CAV-1 protein expression in A549 and NCI-H460 lung cancer cells." (PMID 32733649, 2020). "As we know, SIRT3 localizes to the mitochondria; moreover, interestingly, although the function of SIRT3 in NSCLC has been reported individually, the effects of SIRT3 on lung cancer cells are contradictory in these articles." (PMID 39501597, 2024). "In addition, both were more potent inhibitors of HIF-1 and SIRT-3 than 5-FLU, especially in pancreatic and lung cancers." (PMID 36906524, 2023).
lung carcinoma (continued). "In addition, Melatonin can also activate SIRT3, then the SIRT3/PDH axis is stimulated to improve the ROS production to induce apoptosis of lung cancer cells." (PMID 35832551, 2022). "SIRT3, FOXO3, and CDT1 expression was suppressed in the lung cancer tissues and cells." (PMID 33655712, 2021). "The results showed that after 8Gy irradiation, the expression level of Sirt3 in BEAS-2B cell increased markedly at 8 hours after irradiation, while in lung cancer cells A549 and H1299, the Sirt3 expression level was significantly decreased at 12 hours after irradiation." (PMID 34405009, 2021). "Nonetheless, these inhibitor studies indicate that SIRT-1 and SIRT-3 play pivotal roles in mediating TL-induced down-regulation of CAV-1 protein expression in A549 and NCI-H460 lung cancer cells, further supporting the importance of SIRT-3 in TL-mediated cytotoxicity." (PMID 32733649, 2020). "In this study, we reported for the first time honokiol induced apoptosis, G1 arrest, as well as autophagy mediated cell death in KRAS mutant lung cancer cells, and honokiol blocked KRAS mutant lung cancer cells growth by activating mitochondrial Sirt3 and suppressing HIF-1α expression." (PMID 28443025, 2017). "The tumor suppressor function of SIRT3 gene has been recently described in NSCLC, where it has been shown to inhibit cell proliferation and increase ROS levels in the malignant cells, and to impair tumor development in murine lung cancer models, suggesting an important tumor suppressor gene." (PMID 41441397, 2025). "However, in lung cancer, the role of SIRT3 on immune infiltrate or immune microenvironment has not been studied." (PMID 39501597, 2024). "To further confirm whether FOXO3 is regulated by SIRT3 at acetylated level, we adopted Immunoblotting displayed that compared with normal lung cells, reduced level of SIRT3 and increased ace‐FOXO3 level were observed in lung cancer cells." (PMID 33655712, 2021). "Our findings support the hypothesis that overexpression of SIRT3 elevates FOXO3a/CDT1 axis, thus contributing to inhibited lung cancer cell viability, proliferation, and invasion as well as enhanced cell apoptosis and sensitivity of lung cancer cells to cisplatin." (PMID 33655712, 2021). "However, whether SIRT3 can affect oxidative stress and HIF-1α expression in lung cancer cells by mediating ROS under hypoxic conditions has not been reported." (PMID 37747648, 2023).
Cerebral ischemia (29 papers, 2013 to 2025). Restriction of arterial blood supply to the brain associated with insufficient oxygenation to support the metabolic requirements of the tissue. "SIRT1 overexpression enhances the deacetylation of SIRT3, boosting its activity and improving neurological damage caused by cerebral ischemia-reperfusion injury and mitochondrial dysfunction." (PMID 40356977, 2025). "Downregulation of Sirt3 has been observed during cerebral I/R injury, while ablation of Sirt3 was associated with increased neuronal death and neurological deficits following brain ischemia." (PMID 39844858, 2024). "The accumulation of ceramides induced by SIRT3 is an important cause of cerebral ischemia–reperfusion injury, which is achieved through the activation of deacetylation of CerS1, CerS2, and CerS6 by SIRT3." (PMID 36374406, 2023). "Sirtuin-3 (Sirt3) deacetylates several mitochondrial proteins implicated into cerebral ischemia/reperfusion (I/R) injury." (PMID 37705748, 2023). "In cerebral ischemia, deacetylation of FoxO3a by SIRT3 causes the translocation of FoxO3a into the nucleus and enhancement of FoxO3a-dependent antioxidant protection associated with the activation of catalase and superoxide dismutase 2 (SOD2)." (PMID 35574497, 2022). "We thus further investigated whether cerebral ischemia reperfusion regulates SIRT3 to cause mitochondrial dysfunction and energy metabolism dysfunction." (PMID 37056986, 2023). "Moreover, SIRT3 can promote the accumulation of ceramide, which can worsen the damage caused by cerebral ischemia–reperfusion (I/R)." (PMID 36374406, 2023). "SIRT3 deficiency aggravates cerebral ischemia-induced oxidative stress and neuroinflammation." (PMID 33519419, 2020). "Sirtuin-1 (Sirt1) restores mitochondrial structure and function in rats by activating Sirt3 after cerebral ischemia/reperfusion injury." (PMID 41241701, 2025). "Sirt3 activates the mitochondrial unfolded protein response and reduces cerebral ischemia/reperfusion injury." (PMID 41241701, 2025). "A study showed that upregulating of SIRT3 through the SIRT3-FOXO3a-SOD2 pathway reduced brain ischemia-reperfusion injury and repaired neurons." (PMID 40356977, 2025). "SIRT1 enhances the mitochondrial structure repair and functional recovery by activating SIRT3 after cerebral ischemia/reperfusion injury in rats, thereby promoting neurological function." (PMID 38767771, 2024). "SIRT1 can increase the deacetylation of SIRT3 and enhance the activity of SIRT3 after cerebral ischemia/reperfusion injury." (PMID 38767771, 2024). "Mitochondrial dysfunction contributes to cerebral ischemia–reperfusion (CI/R) injury, which can be ameliorated by Sirtuin-3 (SIRT3)." (PMID 38767771, 2024). "Another study reported the protective effects of melatonin in diabetic mice from cerebral ischemia-reperfusion injury via the Akt/SIRT3/SOD2 pathway leading to improvement in the infarct volume and neurological deficit." (PMID 36675125, 2023). "It has been reported that increased SIRT3 providing neuroprotective effects via enhancing mitochondrial function, increase neuron survival and decrease the number of apoptotic neurons in cerebral ischemia rat through activation of the SIRT3/AMPK/mTOR pathway." (PMID 36111151, 2022). "SIRT1, SIRT2, and SIRT3 have the highest deacetylase activities and can exert great neuroprotective effects in cerebral ischemia." (PMID 33149812, 2020). "Another report found that SIRT3 was responsible for the neuroprotective effects of ketone treatment following cerebral ischemia." (PMID 30450031, 2018). "Additionally, SOD2 activity decreases in response to cerebral ischemia due to protein acetylation regulated by Sirt3." (PMID 39844858, 2024). "However, during the recovery period of cerebral ischemia, SIRT3 KO mice showed a notable decrease in VEGF levels and ERK phosphorylation, and the infarct striatum exhibited lower vascular density." (PMID 37627275, 2023).
Cerebral ischemia (continued). "Furthermore, deficiency of endothelial SIRT3 leads to diastolic dysfunction in aged females, indicating a potential female-specific target for preserving NVC after brain ischemia." (PMID 35431804, 2022). "Mechanically, SIRT3 upregulation protects neurons against cerebral ischemia via AMPK-mTOR pathway." (PMID 33790896, 2021). "SIRT3 has been reported to protect neurons from n-methyl-d-aspartate (NMDA) excitotoxicity, suggesting that SIRT3 may also play a beneficial role in cerebral ischemia." (PMID 32963637, 2020). "SIRT3 protects against oxygen and glucose deprivation by inducing autophagy through activation of the AMPK thus suppressing mTOR pathway in cortical neurons, indicating that SIRT3 may protect neurons from cerebral ischemia." (PMID 30705773, 2019). "It has been purposed that SIRT3 activity could be regulated by mitochondrial uncoupling protein 2 (UCP2) during cerebral ischemia-reperfusion injury by increasing the available NAD+/NADH ratio." (PMID 30450031, 2018). "However, an experiment conducted in 2016 showed that SIRT3 is activated by a currently unknown mechanism and increases the deacetylation level and activity of CerS1, CerS2, and CerS6 after cerebral ischemia–reperfusion." (PMID 36374406, 2023). "SIRT3 has been shown to protect neurons from N-methyl-D-aspartate (NMDA)-induced excitotoxicity, suggesting that SIRT3 might also produce beneficial effects in cerebral ischemia, because NMDA receptor-mediated excitotoxicity plays a crucial role in ischemic brain damage." (PMID 24386592, 2013). "Cerebral ischemia depletes brain tissue NAD+, an essential coenzyme for SIRT3 activity, and administration of nicotinamide mononucleotide (NMN), a precursor of NAD+ protects the brain from ischemic insult." (PMID 36675125, 2023). "The results showed that NAD+ and NBP had similar neuroprotective and antioxidant effects in cerebral ischemia, while NAD+ had better ability in restoring energy metabolism, possibly through upregulating the activity of SIRT1 and SIRT3." (PMID 37056986, 2023). "In a mouse model of cerebral ischemia induced by bilateral common carotid artery occlusion (CCAO), NMN treatment was found to enhance the activity of SIRT3, leading to the suppression of ischemia-induced mitochondrial fragmentation and the generation of ROS." (PMID 37627275, 2023). "Interactions between SIRT3 and PGC-1α depend on the level of oxygen and glucose supply to the tissues, so they provide mechanisms that compensate for cerebral ischemia." (PMID 36289696, 2022). "In addition, Sirtuin-3 (Sirt3), a NAD+-dependent deacetylase, was reported to modulate the UPRmt and attenuate neuroinflammation after cerebral ischemia." (PMID 38321473, 2024). "Furthermore, SIRT3 promoted PINK1/Parkin mediated mitochondrial autophagy, increased microvascular density and the expression of VEGF A, and reduced neuronal apoptosis in cerebral ischemia-reperfusion model rats." (PMID 40969935, 2025). "However, NBP protects cerebral ischemia-reperfusion injury mainly not through SIRT3 to improve mitochondrial function." (PMID 37056986, 2023).